LCK (LCK proto-oncogene, Src family tyrosine kinase)
Diseases named in the same sentence as LCK in open-access papers (continued):
Sharing a sentence is not in itself a finding about the gene and the disease.
endometrioid ovarian cancer (2 papers, 2021 to 2023). "The data indicates that high levels of LCK expression is associated with worse clinical outcomes in endometrioid ovarian cancer and expression of LCK is increased in endometrioid ovarian cancer." (PMID 37370140, 2023). "In endometrioid ovarian cancer, LCK expression is associated with significantly worse median progression-free survival (HR 3.19, p = 0.02)." (PMID 33888137, 2021). "We found an increase in 훾H2AX in LCKi treated CP70 cells.These data indicate that endometrioid ovarian cancer cells exposed to LCKi demonstrate a decrease in phosphorylated LCK and an increase in DNA double strand breaks." (PMID 33888137, 2021). "This compares with half the gene expression of LCK in the predominantly low grade endometrioid ovarian cancer subtype, which showed the most favorable PFS and OS." (PMID 33888137, 2021). "Finally, we demonstrated that LCK disruption is sufficient to sensitize endometrioid ovarian cancer cells to olaparib." (PMID 37370140, 2023). "Further studies are needed to assess the mechanisms behind the enhanced efficacy of pretreatment, as well as further investigation of LCK inhibitors as adjunctive therapy for platinum resistant endometrioid ovarian carcinoma, including other histological subtypes." (PMID 33888137, 2021).
hepatocellular carcinoma (2 papers, 2013 to 2017). A malignant tumor that arises from hepatocytes. "It was found that Vitamin A, retinoid acid and a few other immune response agents modulated by RARA and LCK genes may be potential treatments for both schizophrenia and hepatocellular carcinoma." (PMID 24564241, 2013). "Using a schizophrenia-hepatocellular carcinoma network, the authors found that some schizophrenia candidate genes (SIRPB1, SYK, and LCK) and genes mediating the immune responses in the etiology mechanism of schizophrenia (IL-2 and TREM-1/DAP12) may also function as tumor-suppressor genes." (PMID 29254248, 2017).
HIV-1 infection (2 papers, 2009 to 2014). The type species of lentivirus and the etiologic agent of acquired immunodeficiency syndrome (AIDS). "Having shown that LCK expression in macrophages leads to elevated levels of CD4 at the surface, the impact this has on the different stages of HIV-1 infection was evaluated using a panel of assays as readouts for sequential stages of HIV-1 infection." (PMID 24465876, 2014).
idiopathic pulmonary fibrosis (2 papers, 2018 to 2022). Idiopathic pulmonary fibrosis (IPF) is a nonneoplastic pulmonary disease that is characterized by the formation of scar tissue within the lungs in the absence of any known cause. "Dysregulated expression of genes, including MMP8, in PBMCs of patients with idiopathic pulmonary fibrosis has been reported, and reduced CD28, ICOS, LCK, and ITK gene expression in PBMCs was associated with poor outcome in cohorts with this disorder." (PMID 29445374, 2018). "Considering the condition that the p-value of survival analysis was less than 0.01 and the p-value of expression difference was less than 0.01, we found that ITK, ZAP70, CD247, and LCK were lower expressed in patients with specific pulmonary fibrosis than in healthy controls." (PMID 35774508, 2022).
leprosy (2 papers, 2021 to 2024). Leprosy is a chronic infectious disease affecting primarily the skin and peripheral nervous system. "LCK can determine the T cell signaling via regulating the phosphorylation of various signaling molecules and interact with negative regulators CD45(PTPRC) leadding to T cell hyporesponsiveness in leprosy progression." (PMID 38739634, 2024).
lupus (2 papers, 2022). "Overexpression of LCK contributes to a large number of other diseases such as cancer, systemic lupus erythematosus and organ transplant rejection." (PMID 36341345, 2022).
lymphoid neoplasm (2 papers, 2022). A neoplasm composed of a lymphocytic cell population which is usually malignant (clonal) by molecular genetic and/or immunophenotypic analysis. "LCK activity controls the response to GCs in lymphoid tumors." (PMID 36490346, 2022).
metastatic melanoma (2 papers, 2020 to 2021). A melanoma that has spread from its primary site to another anatomic site. "High LCK protein expression (a T-cell marker) is associated with improved patient survival in primary and/or metastatic melanoma." (PMID 34218795, 2021).
Netherton syndrome (2 papers, 2017 to 2023). Netherton syndrome (NS) is a skin disorder characterized by congenital ichthyosiform erythroderma (CIE), a distinctive hair shaft defect (trichorrhexis invaginata; TI) and atopic manifestations. "Cutaneous viral infections are described in CARD11, LCK, NEMO, GATA2, STK4, DOCK8, and STAT2 deficiencies, STAT1 GOF, Netherton syndrome, WHIM syndrome, and WILD (warts, depressed cell‐mediated immunity, primary lymphedema, and anogenital dysplasia) syndrome." (PMID 37102642, 2023).
Oral squamous cell carcinoma (2 papers, 2021 to 2022). "It has been reported that knockdown of LCK significantly inhibits cell proliferation and cell invasion in Oral squamous cell carcinoma (OSCC)." (PMID 36341345, 2022).
ovarian tumor (2 papers, 2023 to 2024). "Finally, our in vivo studies showed that olaparib efficacy was enhanced in CP70 LCK KO compared to ovarian tumor bearing mice." (PMID 37370140, 2023).
renal carcinoma (2 papers, 2018 to 2019). A carcinoma arising from the epithelium of the renal parenchyma or the renal pelvis. "Src kinase signaling members were also predominant in the core, including SRC, LCK, LYN, FYN and PTPN6, among which LYN has been causally implicated in renal cancer." (PMID 29861861, 2018).
Respiratory tract infection (2 papers, 2017 to 2021). An infection of the upper or lower respiratory tract. "The LCK deficiency is associated to naive CD4+ T-cell lymphopenia, respiratory tract infections, and early-onset autoimmune inflammation." (PMID 28448599, 2017).
sarcoma (2 papers, 2021 to 2024). A usually aggressive malignant neoplasm of the soft tissue or bone. "LCK expression was significantly higher in DSRCT than in all four other fusion sarcomas (p < 0.0001 for all tumors)." (PMID 38177125, 2024).
schizophrenia (2 papers, 2013 to 2017). A major psychotic disorder characterized by abnormalities in the perception or expression of reality. "In summary, the SIRPB1 mediated LCK and SYK gene activation are associated with schizophrenia related to BA22 tissue specific gene." (PMID 24564241, 2013). "SYK and LCK were the over-expression genes with high betweenness, however, SIRPB1 was an over-expressed gene for schizophrenia and directly linked to SYK from the QQPPI of SHCN, and it may have an implication of a potential disease mechanism for schizophrenia." (PMID 24564241, 2013). "The results help to explain that the over-expression genes SIRPB1, LCK and SYK are responsible for one of the possible disease mechanisms for schizophrenia." (PMID 24564241, 2013). "Another responsible pathway involves the IL-2 pathway which Interleukin-2 binds to the IL-2 receptor to activate LCK and SYK, which helps explain that the over-expression genes: SIRPB1, LCK and SYK might be responsible for one of the possible disease mechanisms for schizophrenia." (PMID 24564241, 2013). "For example, the over-expressing schizophrenia candidate genes, SIRPB1, SYK and LCK, are responsible for signal transduction in cytokine production; immune responses involving IL-2 and TREM-1/DAP12 pathways are relevant for the etiology mechanism of schizophrenia." (PMID 24564241, 2013).
ulcerative colitis (2 papers, 2022 to 2025). An inflammatory bowel disease involving the mucosal surface of the large intestine and rectum. "In conclusion, this study provides the first evidence that ceAF can mitigate ulcerative colitis (UC) and TNF-α-induced inflammatory responses by inhibiting the LCK/ZAP70/LAT signaling pathway, thereby reducing TCR signaling hyperactivation." (PMID 39857385, 2025).
uveitis (2 papers, 2025). An inflammatory process affecting a part of or the entire uvea. "Furthermore, there was a significant correlation between patients’ age-specific regulation of genes MYLIP and PDE4A in the uveitis only group and CCR7, LBH, and LCK in the systemic disease-associated uveitis group." (PMID 40270958, 2025).
acute megakaryoblastic leukemia (1 paper, 2022). Acute megakaryoblastic leukemia (AMKL) is a form of acute myeloid leukemia (AML) that occurs predominantly in childhood and particularly in children with Down syndrome (DS-AMKL). "PP1 is a potent and selective Src inhibitor for LCK and Fyn kinase proteins that has been tested against the acute megakaryoblastic leukemia cell line M-07e at 100 nm, 500 nm, 1 μm, 2.5 μm, and 5 μm concentrations." (PMID 36434556, 2022).
allergic asthma (1 paper, 2022). A asthma with a basis in a pathological type I hypersensitivity reaction. "Therefore, this investigative study was designed to determine the role of LCK in a cockroach extract (CE)-induced airway inflammation murine model of allergic asthma." (PMID 36144198, 2022). "Therefore, this study examined the role of LCK and its relationship with downstream signaling pathways in CD4+ T cells in a cockroach extract (CE)-induced airway inflammation model of allergic asthma in mice." (PMID 36144198, 2022).
alopecia areata (1 paper, 2023). Loss of scalp and body hair involving microscopically inflammatory patchy areas. "The up-regulation of the LCK gene is also associated with alopecia areata." (PMID 37359019, 2023).
cholestasis (1 paper, 2024). Impairment of the bile flow caused by obstruction within the liver, or outside the liver in the bile duct system. "Despite the ongoing cholestasis that should attract immune cells, there was no enrichment of LCK+ T cells in Jag1Ndr/Ndr portal areas." (PMID 39358604, 2024).
Chronic colitis (1 paper, 2022). A chronic inflammatory disease of the large intestine (colon, cecum and rectum). "After analyzing the outcome of the mice in the chronic colitis model, we were interested to understand the inflammatory response in the colon tissue and investigated CerS4 WT, KO, and LCK/Cre in an acute DSS model." (PMID 35163788, 2022).
chronic hepatitis (1 paper, 2018). An active inflammatory process affecting the liver for more than six months. "MAP2K7 and MAPK14 were highly expressed in chronic hepatitis; LAT, SOS2, and BCL‐10 were highly expressed in normal tissues; PTPN6, LCK, and CTLA4 were highly expressed in CS." (PMID 30259695, 2018).
chronic kidney disease (1 paper, 2019). Impairment of the renal function secondary to chronic kidney damage persisting for three or more months. "This study shows that cell proliferation, differentiation, apoptosis, migration (SRC, HRAS, HSP90AA1, CDK2), and ameliorating chronic kidney disease (MAPK14, F2, LCK, MMP9) appear to play important roles in the therapeutic effect of SQW." (PMID 31275142, 2019).
Chronic Lymphocytic Leukemia (1 paper, 2022). "Another report stated that inhibition or downregulation of LCK led to apoptosis in Chronic Lymphocytic Leukemia (CLL) cell lines." (PMID 36341345, 2022).
Cirrhosis (1 paper, 2011). A chronic disorder of the liver in which liver tissue becomes scarred and is partially replaced by regenerative nodules and fibrotic tissue resulting in loss of liver function. "It is interesting to note that hub proteins are usually targeted, such as LCK, STAT1 and VCAN in Normal-Cirrhosis network, LCK in Cirrhosis-Dysplasia network, CDC2 and NDC80 in Dysplasia-Early HCC network and Early-Advanced network." (PMID 21824427, 2011). "Additionally, these networks enable us to identify important genes and pathways by developmental stage, such as LCK signalling pathways in cirrhosis, MMP genes and TIMP genes in dysplastic liver, and CDC2-mediated cell cycle signalling in early and advanced HCC." (PMID 21824427, 2011).
clear cell renal carcinoma (1 paper, 2022). A malignant epithelial neoplasm of the kidney characterized by the presence of lipid-containing clear cells within a vascular network. "For example, studies based on gene co-expression network analysis and the Gene Expression Omnibus database showed that LCK was upregulated in clear cell renal carcinoma and correlated with the promotion of tumor progression." (PMID 36430477, 2022).
cognitive decline (1 paper, 2025). "The inclusion of features like CASP9, LCK, and MMSE, highlighted by SHAP analysis, supports early prediction by capturing processes associated with apoptosis, neuroinflammation, and cognitive decline, respectively." (PMID 40228177, 2025).
colitis (1 paper, 2022). Inflammation of the colon. "In conclusion, CerS4 KO and CerS4 LCK/Cre mice were more susceptible to AOM/DSS-induced colitis and CAC than WT mice, whereas CerS4 Vil/Cre mice developed smaller and only preneoplastic tumors in comparison with all other groups." (PMID 35163788, 2022). "However, in the acute inflammation model, the CerS4 KO mice and CerS4 LCK/Cre mice were most susceptible to colitis." (PMID 35163788, 2022). "Summing up, the higher susceptibility of CerS4 KO mice to DSS-induced colitis could be confirmed by increased infiltration of neutrophils and macrophages into the colon tissue of these mice in comparison with that in WT or CerS4 LCK/Cre mice." (PMID 35163788, 2022). "For this, we utilized the azoxymethane/dextran sodium sulphate (AOM/DSS)-induced colitis model in global CerS4 knockout (CerS4 KO), intestinal epithelial (CerS4 Vil/Cre), or T-cell restricted knockout (CerS4 LCK/Cre) mice." (PMID 35163788, 2022). "CerS4 KO and CerS4 LCK/Cre but not CerS4 Vil/Cre mice were more susceptible to the DSS-induced colitis and AOM/DSS-induced CAC." (PMID 35163788, 2022).
common variable immune deficiency (1 paper, 2023). "Two additional studies have shown defective LCK protein expression in the context of severe combined immune deficiency (SCID) and common variable immune deficiency (CVID), respectively." (PMID 38100037, 2023).
endometrioid endometrial adenocarcinoma (1 paper, 2020). "TCGA database analysis showed that in the endometrioid endometrial adenocarcinoma subtype, the prognosis of patients with high LCK expression was significantly better than that of the low expression group." (PMID 33159014, 2020). "Furthermore, the prognostic analysis results showed that in the endometrioid endometrial adenocarcinoma subtype group, the survival rate of patients with high LCK metagene expression was markedly higher than that of the low expression group." (PMID 33159014, 2020).
endothelial dysfunction (1 paper, 2025). In vascular diseases, endothelial dysfunction is a systemic pathological state of the endothelium (the inner lining of blood vessels) and can be broadly defined as an imbalance between vasodilating and vasoconstricting substances produced by (or acting on) the endothelium. "Ibrutinib-specific off-targets LCK, JAK3, and FLT3 were predicted to trigger inflammation processes related to hypertension; ERBB2, BLK, SRC, and CSK were predicted to trigger oxidative stress and endothelial dysfunction; and CSK were predicted to trigger the RAAS overactivation." (PMID 40744952, 2025).
Failure to thrive (1 paper, 2024). Failure to thrive (FTT) refers to a child whose physical growth is substantially below the norm. "Here, we report two siblings homozygous for a novel LCK variant (c.1318C>T; P440S) characterized by T cell lymphopenia with skewed memory phenotype, infant-onset recurrent infections, failure to thrive, and protracted diarrhea." (PMID 37962568, 2024). "We investigated the molecular and cellular effects of a novel LCK variant (c.1318C>T; p.P440S) in two siblings presenting with severe T cell lymphopenia, early-onset viral and fungal infections, failure to thrive, and chronic diarrhea." (PMID 37962568, 2024).
gastric cancer (1 paper, 2022). A primary or metastatic malignant neoplasm involving the stomach. "Classification of gastric cancer based on different immune signatures, such as altered LCK protein expression, predicted tumor responses to PD-1 inhibitors." (PMID 36430477, 2022).
Granuloma (1 paper, 2019). A compact, organized collection of mature mononuclear phagocytes, which may be but is not necessarily accompanied by accessory features such as necrosis. "Among the enrichment score-driving critical genes of the TCR signaling, the levels of transcripts for ITK and its signaling components such as LCK, GRB2, SLP76, NCK1, FYN, and PLCG are significantly upregulated in caseated granulomas compared to uninvolved lung tissue." (PMID 32038633, 2019).
immunotoxicity (1 paper, 2021). "Previous work identified lymphocyte-specific protein tyrosine kinase (LCK) as a critical mediator of immunotoxicity in human B cells following treatment with 2,3,7,8-tetrachlorodibenzo-p-dioxin (TCDD); a high affinity AHR ligand." (PMID 33936048, 2021).
Insulin resistance (1 paper, 2023). Increased resistance towards insulin, that is, diminished effectiveness of insulin in reducing blood glucose levels. "The tyrosine kinase LCK may have an effect on PCOS patients with insulin resistance (IR) and may play an important role in PCOS pathogenesis." (PMID 37537636, 2023).
invasive breast carcinoma (1 paper, 2010). A carcinoma that infiltrates the breast parenchyma. "In the RT–PCR cohort, LCK mRNA expression in invasive breast cancer was 14-fold less than SRC and was associated with improved disease-specific survival in the IHC cohort." (PMID 20717116, 2010).
ischemia (1 paper, 2020). A hypoperfusion of the BLOOD through an organ or tissue caused by a PATHOLOGIC CONSTRICTION or obstruction of its BLOOD VESSELS, or an absence of BLOOD CIRCULATION. "As for the LCK regulation on the cardiovascular disease mechanism, some research reports showed that the LCK activation could play a role in protecting the heart during ischemia." (PMID 33108241, 2020).
liver cancer (1 paper, 2022). An epithelial or non-epithelial malignant neoplasm that arises from the liver. "In this study, decreased expression of LCK in liver cancer was identified, and a high expression of LCK was associated with favorable survival in patients with LIHC." (PMID 36430477, 2022).
liver cirrhosis (1 paper, 2021). "Among them, CCL5, CXCL9, CXCL12, LCK and CD24, which are thought to participate in the immune response, were identified as the most affected genes, suggesting a disruption of the immune response in liver cirrhosis." (PMID 34434654, 2021).
lung diseases (1 paper, 2023). "During symptomatic lung diseases, leptin is the main stimulator of LCK and EGR2 genes, which exacerbates inflammation and activates monocytes, respectively." (PMID 37408184, 2023).
meningioma (1 paper, 2025). A generally slow growing tumor attached to the dura mater. "Additionally, there were eight kinases that were not significantly differently expressed between meningioma and VS present in the macrophages (LCK, PDGFRB, FGFR1, FLT1, CSK, MEK, MAP2K2, and ERBB2)." (PMID 41437121, 2025).
metastatic cancers (1 paper, 2021). A carcinoma which has spread from the original site of growth to another anatomic site. "In fact, earlier studies could demonstrate that the LCK gene encodes antigenic epitopes recognized by HLA class I-restricted and tumor-specific cytotoxic T lymphocytes (CTLs) of metastatic cancer patients." (PMID 34116687, 2021).
neuroblastoma (1 paper, 2023). Neuroblastoma (NB) is the most common solid, extracranial childhood tumor. "We found that in both SCLC and neuroblastoma, cell lines with higher NE scores were more resistant to drugs that target MEK, mTOR, XIAP, LCK, HSP90, and Abl but were more sensitive to BCL inhibitors, which inhibit anti-apoptotic B-cell lymphoma-2 (Bcl-2) family of proteins." (PMID 37255415, 2023).